UAP1L1 (UDP-N-acetylglucosamine pyrophosphorylase 1 like 1)
Tractability: PROTAC: ubiquitination databases record sites on it; its protein half-life has been measured.
Gene: Protein-coding gene on chromosome 9 (137,077,483 to 137,084,542, forward strand). Ensembl gene ENSG00000197355.
Subcellular location (Human Protein Atlas): Intermediate filaments; Cytosol
Gene Ontology:
Molecular function: transferase activity, transferring phosphorus-containing groups; uridylyltransferase activity
Biological process: UDP-N-acetylglucosamine biosynthetic process
Genetic constraint (gnomAD): Loss-of-function variants: 50 observed, 42.35 expected, observed/expected ratio (o/e) 1.18, 90% interval 0.94 to 1.5. The upper end of that interval is the gene's LOEUF score, 1.5, which puts it in group 6 of 6, group 1 being the genes least tolerant of losing a copy. Missense variants: 667 observed, 648.16 expected, observed/expected ratio (o/e) 1.03, 90% interval 0.96 to 1.1. Synonymous variants: 323 observed, 281.71 expected, observed/expected ratio (o/e) 1.15, 90% interval 1.05 to 1.26.
Homologues: Orthologues: chimpanzee UAP1L1 (99% identical), pig UAP1L1 (86% identical), guinea pig UAP1L1 (84% identical), rat Uap1l1 (83% identical), mouse Uap1l1 (82% identical), macaque UAP1L1 (74% identical), tropical clawed frog uap1l1 (66% identical), zebrafish uap1l1 (65% identical), Drosophila melanogaster mmy (48% identical), Caenorhabditis elegans C36A4.4 (35% identical). Paralogues in human: UAP1 (58% identical), UGP2 (20% identical).
Diseases named in the same sentence as UAP1L1 in open-access papers:
UAP1L1 is named in the same sentence as 10 diseases in open-access papers, as found by Europe PMC text mining. Sharing a sentence is not in itself a finding about the gene and the disease. The quoted sentences say what the papers report.
hepatocellular carcinoma (4 papers, 2022 to 2024). A malignant tumor that arises from hepatocytes. "UAP1L1 is significantly upregulated in hepatocellular carcinoma tissues, and a high level of UAP1L1 expression is associated with poor prognosis." (PMID 38054015, 2023). "GPNMB is implicated in immunosuppression and cancer progression, and UAP1L1 plays a critical role in the proliferation of hepatocellular carcinoma cells, whose knockdown significantly decreases human hepatoma cell proliferation." (PMID 37595802, 2023). "UAP1L1 has been reported to correlate with breast tumor patient relapse-free survival, and directly interacts with OGT to mediated hepatocellular carcinoma cell proliferation." (PMID 35168617, 2022).
gastric cancer (3 papers, 2020 to 2023). A primary or metastatic malignant neoplasm involving the stomach. "Further correlation analysis between UAP1L1 expression and tumor characteristics of gastric cancer patients showed its significant association with T stage (T infiltrate), which was also confirmed by Spearman rank correlation analysis." (PMID 32310823, 2020). "More importantly, the Kaplan-Meier survival analysis of the data collected from KM plotter database indicated that high expression of UAP1L1 was significantly associated with poorer prognosis of gastric cancer patients, as well as shorter survival period (P = 0.0006)." (PMID 32310823, 2020). "However, research concerning the functions of UAP1L1 in cancer is still rarely observed and its association with gastric cancer is still unclear." (PMID 32310823, 2020). "Previous studies showed that UAP1L1 acted as a tumor promoter in the progression of gastric cancer by regulating the cell cycle regulator CDK6." (PMID 35168617, 2022). "Collectively, the in vitro studies clearly validated that UAP1L1 plays an important role in the development and progression of gastric cancer." (PMID 32310823, 2020). "In conclusion, this study revealed the abnormal overexpression of UAP1L1 and CDK6 in gastric cancer and the role of UAP1L1/CDK6 axis in gastric cancer progression." (PMID 32310823, 2020). "In this study, among the DEGs screened by a gene expression array, CDK6 was identified as a potential target of the UAP1L1 induced regulation of gastric cancer." (PMID 32310823, 2020). "Altogether, these experimental results and bioinformatics revealed the involvement of UAP1L1 in the development and progression of gastric cancer." (PMID 32310823, 2020). "Despite of the differential expression level, the expression of UAP1L1 was found to be upregulated in gastric cancer cells compared with GES-1 cells." (PMID 32310823, 2020). "We next constructed SGC-7901 cells with mere UAP1L1 overexpression and simultaneous UAP1L1 overexpression + CDK6 knockdown to investigate the synergistic effects of them on gastric cancer." (PMID 32310823, 2020). "In this study, it was found that the expression of UAP1L1 in gastric cancer tissues was generally higher than that in normal tissues." (PMID 32310823, 2020). "In this study, we first investigate the expression of UAP1L1 in human gastric cancer tissues and compared with that in normal tissues to preliminarily estimate its role in gastric cancer." (PMID 32310823, 2020). "The observation and measurement of tumor-bearing mice models further make clear the promotor role of UAP1L1 in the development and progression of gastric cancer, with an unclear mechanism." (PMID 32310823, 2020). "Data mining of TCGA and KM plotter database not only verified the abnormal overexpression of UAP1L1 in gastric cancer, but also built a linkage between UAP1L1 high expression and poor prognosis." (PMID 32310823, 2020). "In this study, we detected the differential expression of UAP1L1 between gastric cancer and normal tissues, revealing the upregulated UAP1L1 level in gastric cancer and the positive relationship between high UAP1L1 expression and more advanced tumor grade." (PMID 32310823, 2020). "Given the clear-cut role of UAP1L1 in the development of gastric cancer, we next explored the downstream mechanism of its regulatory effects on gastric cancer." (PMID 32310823, 2020). "Expression patterns of UAP1L1 in gastric cancer tissues and normal tissues revealed in immunohistochemistry analysis." (PMID 32310823, 2020). "In summary, CDK6 possessed similar regulatory effects on the development of gastric cancer with UAP1L1." (PMID 32310823, 2020). "Subsequent in vitro experiments validated the role of UAP1L1 in gastric cancer via uncovering the inhibition of cell proliferation and cell motility, and the promotion of cell apoptosis induced by UAP1L1 knockdown." (PMID 32310823, 2020).
gastric cancer (continued). "Next, it was demonstrated that gastric cancer cells with downregulated expression of UAP1L1 (shUAP1L1) exhibited significantly slower proliferation rate than the shCtrl group (P < 0.001)." (PMID 32310823, 2020). "The UDP-GlcNAc pyrophosphorylase-1 like 1 (UAP1L1) is another upstream driver of CDK6 in gastric cancer, as the phenotypes observed in UAP1L1 overexpressing cells were reversed in CDK6-silenced cells, suggesting that gastric cancer progression depends on CDK6 activity via multiple pathways." (PMID 36769170, 2023). "Moreover, patients with relatively higher UAP1L1 expression tend to suffer from tumors in more advanced grade, indicating the potential role of UAP1L1 in the development of gastric cancer." (PMID 32310823, 2020). "Relationship between UAP1L1 expression and tumor characteristics in patients with gastric cancer." (PMID 32310823, 2020). "In a word, these results clarified the promotion effects of UAP1L1 overexpression on gastric cancer, in which CDK6 may be involved." (PMID 32310823, 2020). "UAP1L1 was identified as a potential tumor promotor for gastric cancer which possesses the potential to be used as a therapeutic target in the development of more effective treatment for gastric cancer." (PMID 32310823, 2020). "In spite of these, the role of UAP1L1 in human cancers, especially gastric cancer and the underlying mechanism are still not clear." (PMID 32310823, 2020). "The results of IHC analysis showed that the expression level of UAP1L1 in tumor tissues was much higher than that in normal tissues, indicating that UAP1L1 may be involved in the development and progression of gastric cancer." (PMID 32310823, 2020). "More importantly, we found that knockdown of CDK6 could not only directly restrain the development of gastric cancer, but also alleviate even reverse the UAP1L1 overexpression induced promotion of gastric cancer." (PMID 32310823, 2020). "Therefore, we provide powerful evidence of the involvement of UAP1L1 in gastric cancer, which may be used as a novel therapeutic target in the treatment of gastric cancer." (PMID 32310823, 2020). "It was further demonstrated in vitro and in vivo that changes in the expression of UAP1L1 has significant regulatory effects on gastric cancer cell proliferation, apoptosis and motility, and could disturb the tumorigenicity of gastric cancer cells as well as slow down the tumor growth." (PMID 32310823, 2020). "On the other hand, the expression of UAP1L1 in human gastric mucosal epithelial cell GES-1 and various types of gastric cancer cell lines was detected by qPCR." (PMID 32310823, 2020). "Gastric cancer (GC) is one of the most commonly diagnosed malignancies in digestive tract and its underlying molecular mechanism is still not clear, so we aimed to reveal the relationship between GC and UDP-GlcNAc pyrophosphorylase-1 like 1 (UAP1L1)." (PMID 32310823, 2020). "Moreover, this study also aimed to explore the mechanism, by which UAP1L1 promotes the development and progression of gastric cancer, and identified CDK6 as a potential target of UAP1L1." (PMID 32310823, 2020). "Finally, similar with UAP1L1, the expression of CDK6 was found to be significantly higher in gastric cancer cells compared to GES-1 cells." (PMID 32310823, 2020).
glioma (3 papers, 2022 to 2023). A benign or malignant brain and spinal cord tumor that arises from glial cells (astrocytes, oligodendrocytes, ependymal cells). "Among these proteins, only UAP1L1 was related to GBM studies, and the expression of UAP1L1 in glioma tissues was significantly upregulated." (PMID 38054015, 2023). "On the one hand, some glycosylation-related enzymes, such as UAP1L1, have been shown to be upregulated in gliomas; on the other hand, some highly glycosylated proteins have been found." (PMID 37231524, 2023). "Recent studies have found that the expression of UAP1L1 is significantly upregulated in glioma tissues." (PMID 38054015, 2023). "Furthermore, the results of RT-qPCR suggested higher expression of BCKDK and UAP1L1 in TMZ resistant glioma tissues than in TMZ sensitive glioma tissues." (PMID 38054015, 2023). "However, the specific mechanism by which UAP1L1 regulates glioma cell proliferation, apoptosis, and TMZ drug resistance is still poorly understood." (PMID 38054015, 2023). "Furthermore, studies determined that UAP1L1 knockdown inhibited the proliferation of glioma and esophageal squamous cell carcinoma cells and tumor growth in vivo." (PMID 35168617, 2022). "UAP1L1 may promote the proliferation of glioma cells by regulating glycosylation of key proteins." (PMID 38054015, 2023).
liver diseases (1 paper, 2024). "Exogenous molecules, such as curcumin, acetaminophen, and corosolic acid, and endogenous molecules, such as microRNAs, UAP1L1, and SIX1, affect certain liver diseases through the O-GlcNAc metabolic pathway." (PMID 38786029, 2024).
prostate carcinoma (1 paper, 2022). A carcinoma that arises from epithelial cells of the prostate gland. "The results showed that the knockdown of UAP1L1 remarkably enhanced the apoptosis in both prostate cancer cells." (PMID 35168617, 2022). "However, the association of UAP1L1 with prostate cancer and functions remain unclear." (PMID 35168617, 2022). "Subsequently, growth curve analysis showed that knockdown of UAP1L1 expression by lentivirus attenuated the growth of both prostate cancer cells." (PMID 35168617, 2022). "The results indicated that UAP1L1 promoted the proliferation, migration and invasion of prostate cancer cells, which was inhibited by downregulating CDCA8." (PMID 35168617, 2022). "Hence, UAP1L1 might serve as a potential target to predict the risk of prostate cancer progression." (PMID 35168617, 2022). "UAP1L1 knockdown also inhibited the proliferation of prostate cancer cells in vivo and further suppressed the growth of tumor in mice models." (PMID 35168617, 2022). "Correlation analysis between UAP1L1 expression and clinical characteristics in patients with prostate cancer revealed that there were significant differences in the expression of UAP1L1 in pathology grade, Gleason score and Gleason grade." (PMID 35168617, 2022). "Altogether, these results indicated that UAP1L1 knockdown inhibited prostate cancer cell proliferation, invasion and migration in vitro, but induced cell apoptosis probably through regulating the expression of CD40L, IGFBP-3 and p21." (PMID 35168617, 2022). "To explore the role of UAP1L1 in tumor growth, we used lentivirus targeting against UAP1L1 mRNA to suppress the expression of UAP1L1 in prostate cancer cell lines (DU 145 and PC3)." (PMID 35168617, 2022). "In conclusion, the results in this study revealed that UAP1L1 promoted the progression of prostate cancer through the downstream gene CDCA8." (PMID 35168617, 2022). "In the present study, we found UAP1L1 was upregulated in human prostate cancer tissues, and the expression of UAP1L1 was positively correlated with pathology grade, Gleason score and Gleason grade of patients with prostate cancer." (PMID 35168617, 2022). "But the inhibitory effect of shCDCA8 would be weakened, when prostate cancer cells overexpressed UAP1L1 as well as knocked down CDCA8." (PMID 35168617, 2022). "Besides, the regulation mechanism of UAP1L1 in prostate cancer was explored preliminarily, which revealed that UAP1L1 promoted prostate cancer progression by regulating CDCA8." (PMID 35168617, 2022). "The UAP1L1 overexpression, CDCA8 knockdown and UAP1L1 overexpression accompanied by CDCA8 knockdown cell models were constructed successfully in vitro by lentivirus transfection in order to investigate the effects of CDCA8 regulated by UAP1L1 on prostate cancer cells." (PMID 35168617, 2022). "Besides, the overexpression of UAP1L1 promoted the proliferation and migration of prostate cancer cells, which also alleviated the inhibitory effects of CDCA8 knockdown on prostate cancer progression." (PMID 35168617, 2022). "Likewise, the results of this study demonstrated that UAP1L1 knockdown inhibited proliferation, clone formation ability, and migration of prostate cancer cells (DU 145 and PC-3), and promoted the cell apoptosis." (PMID 35168617, 2022). "For the purpose of investigating the role of UAP1L1 in prostate cancer, the expression levels of UAP1L1 in prostate cancer tissues were firstly detected by immunohistochemical staining, which indicated that UAP1L1 was significantly upregulated in prostate cancer tissues." (PMID 35168617, 2022). "UAP1L1 knockdown reduced CDCA8 expression in prostate cancer cells." (PMID 35168617, 2022). "Furthermore, the expression of CDCA8 was upregulated in prostate cancer tissues and inhibited by UAP1L1 knockdown." (PMID 35168617, 2022). "In addition, the expression of UAP1L1 in prostate cancer tissues was obvious higher than normal prostate tissues according to the immunohistochemistry analysis." (PMID 35168617, 2022).
prostate carcinoma (continued). "Above all, UAP1L1 may be related to the process of prostate cancer." (PMID 35168617, 2022). "However, the mechanism of action of UAP1L1 in prostate cancer was still unclear." (PMID 35168617, 2022). "Here we reported the study of UAP1L1 in prostate cancer and provide evidence that UAP1L1 has a critical role in tumorigenesis through targeting CDCA8, which is essential for the growth of at least two prostate cancer cell lines." (PMID 35168617, 2022). "Therefore, UAP1L1/CDCA8 can be used as potential therapeutic target for prostate cancer, providing a new possible strategy for the diagnosis and treatment of prostate cancer." (PMID 35168617, 2022). "In this study, the effects of UAP1L1 (UAP1-like-1) on prostate cancer were investigated by detecting the proliferation, migration, invasion and apoptosis of prostate cancer cells in vitro using MTT, wound healing, Transwell and flow cytometry assay, and the tumor growth in vivo." (PMID 35168617, 2022).
viral infections (1 paper, 2024). "UAP1L1 is essential in the golgi and endoplasmic reticulum (ER) stress responses to oxidative stress, apoptosis, or viral infections." (PMID 39335448, 2024).
tumor (5 papers, 2020 to 2026). "The detection of UAP1L1 expression in GC tumor and normal tissues was accomplished by immunohistochemistry and demonstrated the upregulation of UAP1L1 in GC, which was statistically associated with tumor grade." (PMID 32310823, 2020). "Increased expression of UAP1L1 is associated with higher tumor grade and poor prognosis." (PMID 38054015, 2023). "The representative images of solid tumor obtained from mice clearly showed a reduced speed of tumor growth after UAP1L1 downregulation." (PMID 35168617, 2022). "For further verifying the influence of UAP1L1 knockdown on tumor growth in vivo, mice xenograft models were constructed through subcutaneous injection of SGC-7901 cells transfected with shUAP1L1 or shCtrl." (PMID 32310823, 2020). "Consistently, the RNA-seq data collected from TCGA-STAD database of The Cancer Genome Atlas (TCGA) also demonstrated a 2.21-fold higher UAP1L1 expression in tumor tissues compared with normal tissues (P < 0.001)." (PMID 32310823, 2020). "The much stronger bioluminescence intensity in mice of shUAP1L1 groups than that of shCtrl group also proved the suppression of tumor growth by UAP1L1 knockdown in vivo (P < 0.001)." (PMID 32310823, 2020). "In conclusion, UAP1L1 was reported to be a tumor promotor in the development and progression of GC which may exert its role through regulating CDK6 and may act as a candidate of therapeutic target in treatment." (PMID 32310823, 2020). "Moreover, western blotting demonstrated the downregulated expression of UAP1L1 and CDK6, and upregulated expression of E-cadherin and ZO-1 in tumor tissues collected from shUAP1L1 group." (PMID 32310823, 2020).
cancer (4 papers, 2019 to 2023). A tumor composed of atypical neoplastic, often pleomorphic cells that invade other tissues. "The results showed that the lentivirus was efficiently transfected into DU 145 and PC3 cells, and the qPCR analysis and WB assay identified that the expression of UAP1L1 was significantly inhibited in both cancer cells." (PMID 35168617, 2022). "Considering the important role played by glycosylation in various biological processes and the involvement of changes in protein glycosylation in malignant tumors, it was predicted that UAP1L1 would also participate in the development and progression of human cancers." (PMID 32310823, 2020).
UAP1L1 also shares sentences with these, for which no sentence is quoted: bladder cancer (1 paper); esophageal squamous cell carcinoma (1).